SRI (sorcin)
Description:
Calcium-binding protein that modulates excitation-contraction coupling in the heart. Contributes to calcium homeostasis in the heart sarcoplasmic reticulum. Modulates the activity of RYR2 calcium channels.
Synonyms: CP22; CP-22; SCN; V19
Tractability: Small molecule: a structure with a bound ligand is known; it has a high-quality binding pocket. Antibody: UniProt places it where antibodies can reach, with medium confidence; its Gene Ontology location is reachable by antibodies, with medium confidence. PROTAC: ubiquitination databases record sites on it; its protein half-life has been measured.
Gene: Protein-coding gene on chromosome 7 (88,205,115 to 88,226,993, reverse strand). Ensembl gene ENSG00000075142.
Subcellular location: Cytoplasm; Sarcoplasmic reticulum membrane
Subcellular location (Human Protein Atlas): Cytosol; Nucleoplasm
Pathways (Reactome):
Transport of small molecules: Ion transport by P-type ATPases; Sodium/Calcium exchangers; Stimuli-sensing channels
Hemostasis: Reduction of cytosolic Ca++ levels
Muscle contraction: Ion homeostasis
Gene Ontology:
Molecular function: calcium ion binding; protease binding; protein binding; protein heterodimerization activity; calcium channel regulator activity; DNA-binding transcription factor binding; protein sequestering activity; signaling receptor binding; transcription regulator inhibitor activity; transmembrane transporter binding
Biological process: negative regulation of heart rate; regulation of calcium ion transport; regulation of cardiac muscle cell contraction; regulation of cell communication by electrical coupling involved in cardiac conduction; regulation of relaxation of muscle; regulation of release of sequestered calcium ion into cytosol by sarcoplasmic reticulum; positive regulation of release of sequestered calcium ion into cytosol; regulation of cell communication by electrical coupling; regulation of insulin secretion involved in cellular response to glucose stimulus; signal transduction; negative regulation of cardiac muscle contraction; regulation of gene expression
Cellular component: chromaffin granule membrane; cytosol; endoplasmic reticulum membrane; extracellular exosome; membrane; Z disc; cytoplasm; sarcoplasmic reticulum; T-tubule; plasma membrane; sarcoplasmic reticulum membrane; vesicle
Genetic constraint (gnomAD): Loss-of-function variants: 30 observed, 30.66 expected, observed/expected ratio (o/e) 0.98, 90% interval 0.73 to 1.33. The upper end of that interval is the gene's LOEUF score, 1.33, which puts it in group 5 of 6, group 1 being the genes least tolerant of losing a copy. Missense variants: 242 observed, 251.27 expected, observed/expected ratio (o/e) 0.96, 90% interval 0.87 to 1.07. Synonymous variants: 75 observed, 90.58 expected, observed/expected ratio (o/e) 0.83, 90% interval 0.69 to 1.
Homologues: Orthologues: macaque SRI (99% identical), dog SRI (99% identical), pig SRI (99% identical), mouse Sri (96% identical), chimpanzee SRI (91% identical), guinea pig SRI (90% identical), rat Sri (89% identical), tropical clawed frog sri (78% identical), zebrafish sri (70% identical), Caenorhabditis elegans clp-8 (24% identical), Caenorhabditis elegans tra-3 (19% identical), Caenorhabditis elegans clp-6 (15% identical), and 5 more. Paralogues in human: GCA (62% identical), CAPN8 (40% identical), PEF1 (39% identical), CAPN2 (38% identical), CAPN1 (38% identical), CAPN3 (37% identical), CAPN11 (36% identical), CAPN9 (35% identical), CAPN12 (34% identical), CAPNS1 (30% identical), CAPN14 (29% identical), CAPN13 (27% identical), and 8 more.
Diseases named in the same sentence as SRI in open-access papers:
SRI is named in the same sentence as 58 diseases in open-access papers, as found by Europe PMC text mining. Sharing a sentence is not in itself a finding about the gene and the disease. The quoted sentences say what the papers report.
breast carcinoma (11 papers, 2014 to 2025). "Cell death upon decrease in sorcin expression dovetails with the high levels of sorcin expression associated with multiple myeloma, lymphoma, breast cancer and other cancers, and with sorcin upregulation in Multi Drug Resistant (MDR) tumor cells which are resistant to apoptosis onset." (PMID 24427308, 2014). "Sorcin has been found to be overexpressed in many cancers such as leukemia, stomach, lung, ovarian, and breast cancers." (PMID 40611756, 2025). "Downregulation of SRI promotes apoptosis in breast cancer and leukemia, while overexpression of SRI increases the resistance to apoptosis in leukemia K562 cells." (PMID 39000312, 2024). "Leukemia and breast carcinoma cells overexpressing sorcin also showed high expression of Bcl-2, along with decreased level of Bax; upon sorcin silencing, cells show increased Bax, c-fos and c-jun expression, while the level of Bcl-2 is decreased." (PMID 39199583, 2024). "Sorcin transfection in several tumor cell lines (leukemia, lung, gastric, ovarian, and breast cancers) increases resistance to common chemotherapy drugs, e.g., paclitaxel, doxorubicin, vincristine, etoposide, 5-fluorouracil and homoharringtonine." (PMID 39199583, 2024). "Sorcin silencing in the breast cancer cells decreases the pool of CD44+/CD24– and ALDH1 high CSCs in vitro." (PMID 34869449, 2021). "Sorcin has been found to over expressed in many cancers such as leukemia and gastric, ovarian and breast cancers." (PMID 29262638, 2017). "We have analyzed Sorcin expression in different cell lines from lung, cervix and breast cancers and we evidenced that Sorcin is expressed in all tested cell lines, but the levels differ even by more than one order of magnitude between different lines." (PMID 28726784, 2017). "Using 2-DE and western blot analysis, sorcin was identified in the blood serum of human breast cancer subjects and new insights into the manner by which the expression levels of sorcin affect the outcome of NAC have been presented." (PMID 25364401, 2014). "Sorcin regulates epithelial-to-mesenchymal transition and breast cancer metastasis in vivo." (PMID 35600402, 2022). "IHC has been used to study the expression of sorcin in breast cancer tissue." (PMID 25364401, 2014). "As sorcin is considered a pivotal breast cancer resistance-related protein, understanding the mechanisms of sorcin at a molecular level may have a significant impact on the clinical management of breast carcinoma." (PMID 25364401, 2014). "To conclude, the upregulation of sorcin in the serum of breast cancer patients may be partially responsible for the development of multidrug resistance." (PMID 25364401, 2014). "It was hypothesized that the expression level of sorcin in breast cancer may predict the efficiency of the paclitaxel/epirubicin regimen in NAC." (PMID 25364401, 2014). "Since sorcin is recognized as an important protein related to breast cancer resistance, understanding the mechanisms of sorcin at the molecular level may have a significant impact on the clinical management of patients with PCa, which has many aspects similar to breast cancer." (PMID 40611756, 2025). "On the other hand, sorcin is related to epithelial-to-mesenchymal (EMT) transition, which contributes to cancer metastases, as in breast cancer and colorectal cancer." (PMID 29262638, 2017). "Sorcin overexpression by gene transfection increased drug resistance to a variety of chemotherapeutic agents in K562 cells, SGC7901 cells, ovarian and breast cancer." (PMID 28726784, 2017). "In particular, Sorcin is highly expressed in lung cancer cell lines Calu-1 and H1299, that we have selected for further studies, and in breast cancer cell lines MDA-MB-231 and MDA-MB-468, while low Sorcin expression levels were observed in lung A549 and in cervical cancer HeLa cells." (PMID 28726784, 2017).
breast carcinoma (continued). "The 2-DE analysis of the pooled sample serum of breast cancer patients revealed the upregulation of sorcin in >70% of all participants who did not respond to NAC (those with PD)." (PMID 25364401, 2014). "Sorcin silencing inhibits the epithelial-to-mesenchymal transition in the breast cancer MDA-MB-213 cell line, possibly via E-cadherin and VEGF expression, and reduces breast cancer metastasis, while sorcin overexpression increases migration and invasion in vitro." (PMID 25197934, 2014). "To date, the overexpression of sorcin has been observed in a number of multidrug-resistant (MDR) cell lines and several tumor cell types, including human colorectal cancer cells, human gastric cancer cells, leukemia, ovarian and breast cancer cells and lung cancer." (PMID 25364401, 2014). "NAC moderately reduces sorcin expression; however this does not occur in all breast cancer cases." (PMID 25364401, 2014).
leukemia (8 papers, 2014 to 2024). A malignant (clonal) hematologic disorder, involving hematopoietic stem cells and characterized by the presence of primitive or atypical myeloid or lymphoid cells in the bone marrow and the blood. "SRI encodes Sorcin, a calcium-binding protein that has been associated with increased tumor aggressiveness and can induce ABCB1 expression in leukemia." (PMID 38163893, 2024). "Conversely, sorcin silencing reverses MDR in leukemia, HeLa, breast, and colorectal cancer and nasopharyngeal carcinoma." (PMID 32268494, 2020). "Sorcin is upregulated in many cisplatin-resistant cancers and tumor cell lines, such as leukemia, nasopharyngeal carcinoma, and lung cancer, while sorcin silencing increases cisplatin cytotoxicity and glutathione depletion." (PMID 32268494, 2020). "Sorcin is overexpressed in many human tumors, such as leukemia, lymphoma, adenocarcinoma, gastric, lung, breast, nasopharyngeal and ovarian cancers, and especially in MDR cancers." (PMID 25197934, 2014). "The level of sorcin expression in leukemia patients inversely correlates with patients response to chemotherapies and overall prognosis." (PMID 25197934, 2014). "In these cells, sorcin silencing increases cytosolic calcium and increases cell death by apoptosis, while sorcin overexpression in K562 leukemia cells significantly reduces cytosolic Ca2+ levels, thus protecting cells from etoposide-dependent apoptosis, upregulates Bcl-2 and decreases Bax." (PMID 32268494, 2020). "In fact, sorcin is overexpressed in many human cancers, as lymphomas, leukemias, gastric, breast, lung, nasopharyngeal, ovarian tumors, adenocarcinoma, glioblastoma, astrocytoma, oligodendroglioma, and multidrug (MD)-resistant tumors, with respect to normal tissues." (PMID 32268494, 2020). "Sorcin transfection in different cancer cell lines, such as leukemia, lung, gastric, ovarian, and breast tumors, leads to increased drug resistance to chemotherapeutic drugs such as doxorubicin, vincristine, paclitaxel, etoposide, homoharringtonine, and 5-fluorouracil." (PMID 32268494, 2020). "Moreover, it has been demonstrated that Sorcin overexpression is related to a poor clinical outcome in leukemia patients, and the combination of Sorcin silencing or depletion and chemotherapy treatment improves the effectiveness of treatment and the sensitivity to death stimuli." (PMID 33946271, 2021). "Sorcin overexpression leads to increased ABCB1 levels, ultimately enhancing drug resistance in various cancer cell lines, including those from gastric cancer, lung tumors, nasopharyngeal carcinoma, cervical carcinoma, and leukemias, while sorcin silencing reduces ABCB1 expression." (PMID 39199583, 2024). "Sorcin overexpression increases ABCB1 expression, determining increased drug resistance to several drugs, while sorcin silencing decreases expression of ABCB1, increasing cell death, in gastric cancer cells, lung tumor cells, nasopharyngeal carcinoma, cervical carcinoma cells, and leukemias." (PMID 32268494, 2020).
gastric cancer (6 papers, 2017 to 2025). A primary or metastatic malignant neoplasm involving the stomach. "Sorcin overexpression is tightly associated with the increased local invasion and lymph node metastasis of gastric cancer." (PMID 34869449, 2021). "HPA immunohistochemistry confirmed higher TMEM176A and SRI protein levels in gastric cancer versus adjacent mucosa." (PMID 41228276, 2025). "Sorcin overexpression in gastric cancer tissue is related closely to the depth of invasion, staging severity of malignant tumors, and lymph node metastasis of gastric cancers." (PMID 32268494, 2020). "Mechanistically, sorcin silencing effectively decreased the expression of matrix metalloproteinases 2 and 9 (MMP2 and MMP9), and eventually suppressed gastric cancer metastasis." (PMID 34869449, 2021).
hepatocellular carcinoma (5 papers, 2017 to 2024). A malignant tumor that arises from hepatocytes. "In hepatocellular carcinoma, sorcin is considerably upregulated and caspase-1, GSDMD-N and IL-1β are significantly decreased." (PMID 39616223, 2024). "The interaction between sorcin and Annexin 7, both overexpressed in hepatocellular carcinoma, is able to promote EMT, migration, invasion, and proliferation, contributing to tumor aggressiveness." (PMID 39199583, 2024).
glioma (4 papers, 2010 to 2024). A benign or malignant brain and spinal cord tumor that arises from glial cells (astrocytes, oligodendrocytes, ependymal cells). "Immunohistochemical staining showed high expression of DNCH2, ARHGEF6, NPM1, and SRI, while low expression of NRGN and TM4SF2 in gliomas." (PMID 38427106, 2024).
infertile (3 papers, 2014 to 2025). "The altered regulation of Sorcin might cause imbalance in Ca+2 levels and might result in inadequate functioning of endometrium leading to infertility." (PMID 25405865, 2014). "De-regulation of the expression of Sorcin, Cofilin-1, Apo-A1 and Ran, during early- to mid-secretory phase may have physiological significance and it may be one of the causes for altered differentiation and/or maturation of endometrium, in women with unexplained infertility." (PMID 25405865, 2014). "Immunolocalization experiment showed the down-regulated expression of Sorcin in stroma in mid-secretory phase as compared to early-secretory phase in case of infertile women." (PMID 25405865, 2014). "Sorcin, Cofilin-1, Apo-A1 and Ran were performed in separate endometrial biopsy samples from infertile women." (PMID 25405865, 2014). "Sorcin is highly expressed in the endometrium, during the window of implantation, and decreased sorcin levels are observed in the endometrium of women with unexplained infertility." (PMID 39199583, 2024). "Image analysis revealed the down-regulated expression of sorcin in stroma (3.33 fold), luminal epithelium (LE) (1.6 fold) and glandular epithelium (GE) (2 fold) of mid-secretory phase (LH+7) as compared to stroma, LE, and GE of early-secretory phase (LH+2) endometrium of infertile women." (PMID 25405865, 2014).
ovarian carcinoma (3 papers, 2021 to 2024). A malignant neoplasm originating from the surface ovarian epithelium. "In ovarian cancer, sorcin overexpression is associated with an impaired TGF-β signaling pathway." (PMID 39199583, 2024). "In this study, our analysis showed that the amplification was associated with the high mRNA and protein level of SRI in ovarian cancer, which indicated the sorcin overexpression in ovarian cancer might be due in part to the SRI genomic amplification." (PMID 34869449, 2021). "Triptolide, a diterpenoid epoxide from the thunder god vine, Tripterygium wilfordii, has proapoptotic activity and anti-tumor effects in ovarian cancer cells, reducing the expression of sorcin, MMP-2, and VEGF, which are usually highly expressed in ovarian cancer cells." (PMID 39199583, 2024). "Since sorcin overexpression in ovarian cancer is associated with an impaired TGF-β signaling pathway, this pathway may represent a target to regulate sorcin expression." (PMID 39199583, 2024). "The LANP-PTX-siSRI decreased sorcin expression and increased intracellular calcium, leading to the inhibition of PTX-resistant ovarian cancer cell growth." (PMID 39199583, 2024). "Sorcin (SRI) is a soluble resistance-related calcium-binding protein involved in chemoresistant processes and is overexpressed in many chemoresistant cancer cells, including paclitaxel (PTX)-resistant ovarian cancer." (PMID 35799174, 2022).
Alzheimer disease (2 papers, 2020 to 2021). A progressive, neurodegenerative disease characterized by loss of function and death of nerve cells in several areas of the brain leading to loss of cognitive function such as memory and language. "In fact, it has been shown that sorcin interacts with presenilin 2, a component of the γ-secretase, which is involved in the generation of 39–42 amino acid amyloid-β peptides (Aβ) from cleavage of the Aβ protein precursor in Alzheimer’s disease (AD)." (PMID 34205207, 2021). "Sorcin expression was also assessed in cortex samples from young and old controls (CTRY, CTRO), patients with Down syndrome (DS) and patients with Down syndrome and with Alzheimer’s Disease (DSAD)." (PMID 33060591, 2020).
cardiac arrhythmia (2 papers, 2019 to 2025). Any disturbances of the normal rhythmic beating of the heart or MYOCARDIAL CONTRACTION. "Sorcin seems to be a key RyR2-associated protein under stress conditions since its ablation displayed a significantly higher incidence of cardiac arrhythmias and sudden death in sorcin-KO mice when subjected to acute or chronic stress challenge." (PMID 32038301, 2019).
colorectal cancer (2 papers, 2014 to 2021). A primary or metastatic malignant neoplasm that affects the colon or rectum. "TRAP1 exerts a role in MDR in cancer cells and is upregulated together with Sorcin in colorectal carcinoma cells; moreover, their interaction is required for Sorcin localization at mitochondria and TRAP1 stability." (PMID 33946271, 2021). "On the other hand, inhibition of sorcin expression by sorcin-targeting RNA interference led to reversal of drug resistance in the following cell lines: MDR K562/A02 and sorcin-transfected K562; MCF-7/A02; HeLa; colorectal cancer; and CNE2/DDPls." (PMID 25197934, 2014).
dyslipidemia (2 papers, 2020 to 2021). "Our in vivo observations proposed high sucrose diet to reduce hepatic sorcin levels and enable enhanced cytosol-nuclear shuttling of ChREBP, eventually causing hepatic dyslipidemia." (PMID 33930463, 2021). "Sorcin is a protein involved in maintaining calcium within the endoplasmic reticulum by inhibiting ryanodine receptor activity; its impairment is associated with metabolic syndromes." (PMID 32727501, 2020).
Huntington disease (2 papers, 2020). Huntington disease (HD) is a rare neurodegenerative disorder of the central nervous system characterized by unwanted choreatic movements, behavioral and psychiatric disturbances and dementia. "Sorcin is overexpressed in seven human and mouse models of Huntington’s disease, under the control of the ERSE-I (ER stress response element) promoter upstream sorcin gene, together with other proteins involved in ER stress and unfolded protein response." (PMID 32268494, 2020). "Further, Sorcin is among the genes overexpressed in 7 human and mouse models of Huntington’s disease, under the control of the ERSE-I (ER stress response element) promoter upstream Sorcin gene, together with other proteins involved in ER stress and unfolded protein response." (PMID 33060591, 2020).